SLC1A5 (solute carrier family 1 member 5)
Diseases named in the same sentence as SLC1A5 in open-access papers (continued):
Sharing a sentence is not in itself a finding about the gene and the disease.
tumor (continued). "A study showed that berberine suppressed Hep3B and BEL-7404 cell proliferation by inhibiting glutamine uptake via suppressing SLC1A5 (a glutamine transporter) in vitro, and it could inhibit the tumor xenografts growth in vivo and reduce the expression of SLC1A5." (PMID 35889396, 2022). "Elucidation of the correlation of SLC1A5 with tumor immune-cell infiltration might help in understanding the mechanisms of response and resistance to the respective inhibitors, ultimately paving the way for development of predictive biomarkers and novel treatments." (PMID 34367941, 2021). "Thus, it could be concluded, that the SLC1A5 protein has functions important for cell cycle regulation, tumor suppression, apoptosis and angiogenesis." (PMID 28609484, 2017). "Furthermore, our results showed that suppressing SLC1A5 inhibited the relative tumor volume." (PMID 29100325, 2017). "Furthermore, in vivo experiments indicated that suppression of SLC1A5 could inhibit relative volume of xenografted tumor." (PMID 29100325, 2017). "To investigate whether the expression pattern of SLC1A5 is altered during tumorigenesis of ccRCC, we evaluated SLC1A5 expression levels in normal kidney tissues (n = 3), ccRCC tumor tissues (n = 10) and corresponding peri-tumor tissues (n = 10) by qRT-PCR analysis." (PMID 26599282, 2015). "In CRC tissues, PHGDH, SLC1A5 and SLC38A2 were mainly expressed in tumour cells and the GCs of mature TLSs." (PMID 40660426, 2025). "Moreover, it has recently been shown that the Solute Carrier Family 1 Member 5 (SLC1A5) transporter, which allows the entry of glutamine into the mitochondria, had an oncogenic role since its in vitro inactivation was associated with a reduction of tumor growth." (PMID 40771659, 2025). "SLC1A5 (ASCT2) is mostly upregulated, facilitating glutamine uptake to support KRAS-driven tumour growth, making it a prognostic and therapeutic biomarker." (PMID 41154605, 2025). "When comparing the levels of SLC1A5 mRNA expression in the intrinsic (PAM50) subtypes, high expression was observed in basal, HER2-enriched and luminal B tumours (P < 0.001)." (PMID 39843491, 2025). "Of note, we found more pronounced upregulation of SLC1A5 and SLC7A5 in tumor tissues compared to BPH in response to GLS1 inhibition." (PMID 40707944, 2025). "While the exact transporters involved in serine uptake within tumours remain incompletely defined, members of the solute carrier (SLC) superfamily, such as SLC1A4 (ASCT1), SLC1A5 (ASCT2), SLC7A10, SLC38A2, SLC38A4 and SLC38A5, have been implicated." (PMID 40660426, 2025). "Beyond genetic and epigenetic alterations, amino acid transporter-driven metabolic reprogramming—mediated by LAT1 (SLC7A5), ASCT2 (SLC1A5), and xCT (SLC7A11)—supports tumor proliferation, redox homeostasis, and immune escape." (PMID 41226775, 2025). "Disrupting Gln uptake via SLC1A5, SLC7A5, or SLC38A1 depletion, or by inhibiting GLS, enhances oxidative stress and curtails DNA damage repair, thereby sensitizing tumor cells to ionizing radiation." (PMID 40707944, 2025). "Consistent with cohort 1, the expression patterns of PHGDH, SLC1A5 and SLC38A2 in normal and tumour tissues from cohort 2 were identical for all three markers." (PMID 40660426, 2025). "SLC7A11 gene expression is positively correlated with other amino acid transporters like SLC3A2, SLC1A5, GLS, and the infiltration of neutrophils and macrophages, suggesting that SLC7A11 plays a coordinated role in metabolic regulation and tumor immunity." (PMID 39973065, 2025). "One study demonstrated that apatinib inhibited the expression of GLS1, activated the GCN2/eIF2α/ATF4 pathway, and promoted the expression of SLC1A5, thereby reprogramming Gln metabolism in NSCLC and weakening the response of tumor cells to apatinib." (PMID 40276500, 2025). "When investigating the expression of SLC1A5 protein in biological subtypes, high expression was only predictive of shorter BCSS in luminal B tumours (P < 0.05)." (PMID 39843491, 2025).
tumor (continued). "The correlation between SLC1A5 and GLUD1, which is involved in the conversion of Gln to alpha-ketoglutarate for the TCA cycle and subsequent gluconeogenesis, in luminal A tumours suggests that Gln is utilised for this process." (PMID 39843491, 2025). "SLC1A5-mediated glutamine uptake supports the metabolic demands of rapidly proliferating CRC cells, contributing to tumour growth and survival." (PMID 41154605, 2025). "A previous study showed that the higher the expression of SLC1A5 in HNSCC tumor cells, the lower the infiltration of CD8+ T cells, even though SLC1A5 expression is irrelevant to patient survival." (PMID 39223142, 2024). "CAF-secreted Gln is taken by tumor cells that highly express the Gln transporters SLC1A5 and SCL38A2 and is utilized to maintain tumor growth." (PMID 39199642, 2024). "This is consistent with the absence of proliferation defects upon KD of the major amino acid transporters (SLC1A5, SLC7A1, SLC7A5 and SLC7A11) in K562 tumours." (PMID 38605144, 2024). "In 50 paired tumors and adjacent non-tumor tissues from TCGA COREAD database, 27 of 50 (54 %) CRC samples showed upregulation of SLC1A4, SLC1A5, SLC7A11 and SLC3A2 simultaneously, and 17 of 50 (34 %) CRC samples showed upregulation of three transporter genes." (PMID 39079386, 2024). "Various SLCs can transport glutamine, but specifically, ASCT2 (SLC1A5) has gained interest as a target for inhibiting glutamine uptake, given its general overexpression in tumor tissue and its use as a prognostic biomarker." (PMID 38399253, 2024). "First, exposure of normal lung epithelial cell line (NL-20) to REVs and SEVs for 48 hours resulted in increased expression of SLC1A5, EMT marker Vimentin, and other tumor markers." (PMID 39431017, 2024). "Combining an SLC1A5 inhibitor with an immune checkpoint inhibitor (ICI) can relieve immunosuppression and inhibit tumor growth." (PMID 36902506, 2023). "Tumor cells utilize specific transport proteins, such as SLC1A5 or ASCT2, to efficiently transport glutamine into the cell." (PMID 38202722, 2023). "Existing SLC transporter inhibitors mostly focused on tumor cells, and targeting SLC1A5, SLC3A2, or SLC7A5 has shown anti-tumor efficacy." (PMID 37277776, 2023). "All these results were obtained by double suppression of ASCT2 (SLC1A5) and GLUL in B16F10 and CAFs cells with reprogramming of TME metabolism, which further eliminated tumor ECM and increased nanodrug penetration." (PMID 37420266, 2023). "It was also reported that the suppression of glutamine transporter ASCT2 (also known as SLC1A5) decreased glutamine uptake in vitro and significantly inhibited tumor growth and metastasis in vivo." (PMID 36998464, 2023). "In a lung orthotopic tumor mouse model, the complex PGS/siRNA predominantly accumulated in the lungs, which possess high expression of SLC1A5, and decreased the tumor growth." (PMID 36839686, 2023). "V-9302, a glutamine transporter inhibitor targeting SLC1A5/ASCT2, has validated the effect of attenuating tumor cell proliferation and increasing the infiltration of CD8+T cells." (PMID 37635935, 2023). "Glutamine enters tumor cells by SLC1A5 (ASCT2), SLC38A1, SLC38A2, SLC6A14 (ATB0+), and SLC6A19 (B0AT1), which are frequently overexpressed in different malignancies." (PMID 38001865, 2023). "With the rise and deepening of glutamine metabolism research, SLC1A5 (ASCT2) has gradually become known as the main glutamine transporter, and increasing evidence has shown that SLC1A5 plays important roles in tumour metastasis." (PMID 37829798, 2023). "In Burkitt lymphoma, MYC increased the expression of both SLC1A5 and SLC7A5, promoted glutaminolysis and led to augmented tumor proliferation." (PMID 37032776, 2023). "This proved that the promotion and inhibition of tumour metastasis by ABHD11-AS1 and miR-199a-5p were achieved through SLC1A5." (PMID 37829798, 2023).
tumor (continued). "Essentially, they confirmed that circ-LDLRAD3 regulates SLC1A5 by sponging miR-137 in NSCLC cells, thereby regulating tumor cell proliferation, apoptosis, and mobility." (PMID 35757505, 2022). "The similar results were obtained in tumor samples that protein levels of c-Myc, GLS1, and SLC1A5 were decreased upon treatment with QCSL." (PMID 35058981, 2022). "Through Tumor immune estimation resource (TIMER) analysis, The Arm-level deletion/gain and High Amplification of SLC1A5 can lead to changes in infiltration levels of immune cells." (PMID 35835721, 2022). "We found that SLC1A5 and SPP1 are mainly produced by tumor cells while LGALS9 and PTGER4 are mainly expressed in TAMs." (PMID 36476645, 2022). "Taken together, P-LPK-CPT is highly effective for CRC and deserves further development as a promising anti-tumor therapeutic for CRC, especially SLC1A5-high expression type." (PMID 36376440, 2022). "The analyses revealed that the LCN2 gene and its isoform ENST00000277480.6 showed a positive correlation only with protein cluster 2 comprising EPPK1 and ECADHERIN (tumor group 1) and SLC1A5 and GCN5L2 (tumor group 6)." (PMID 36211450, 2022). "Immunohistochemistry also validated expressions of SLC1A5 and SLC7A5 in MM tumor specimens from both mouse xenografts, S1C) and MM patients." (PMID 35036082, 2022). "Components of the amino acid metabolism such as SLC1A5 and GOT2 showed a similar behavior and were higher expressed in the Wnt‐high tumor entities." (PMID 35904277, 2022). "Solute carrier family 1 member 5 (SLC1A5), also referred to as ASCT2, is a sodium channel that acts as a high-affinity glutamine transporter in tumor cells." (PMID 34708125, 2021). "Studies have reported that SLC7A5, SLC1A5, SLC3A2, SLC43A1 and SLC43A2 are the major BCAA transporters in tumor cells." (PMID 33882453, 2021). "We also found that inhibition of SLC1A5 enhanced the inhibitory effect of Almonertinib on NSCLC cells, which supported the idea of targeting tumor metabolic pathways to improve drug sensitivity." (PMID 34054543, 2021). "There are several glutamine exchangers (ASCTs and Na+-coupled neutral amino acid transporters (SNATs)) that are often overexpressed by tumor cells (e.g., ASCT2 — SLC1A5; SNAT1 — SLC38A1, SNAT2 — SLC38A, and SNAT5 — SLC38A5)." (PMID 35029792, 2021). "Solute carrier family 1 member 5 (SLC1A5) is a major glutamine transporter and plays a key role in tumor growth." (PMID 34367941, 2021). "SLC1A5/ASCT2 inhibitors have been identified and exhibit promising anti-tumor properties in preclinical models." (PMID 33669382, 2021). "Other inhibitors of SLC1A5, such as 6-diazo-5-oxo-l-norleucine (DON), benzylserine, and L-γ-glutamyl-p-nitroanilide (GPNA), also showed suppression of tumor growth." (PMID 34367941, 2021). "Upregulated expression of SLC7A11 (10/14), SLC1A5 (7/14), SLC7A5 (6/14), and SLC3A2 (5/14) was observed in most of the tumor tissues; however, GLS in LUSC, KIRC, and KICH and GLS2 in KIRC and LIHC, were significantly downregulated." (PMID 34573287, 2021). "The ASCT2 (SLC1A5) is expressed in most human tissues including the large intestine and CRC tumor cells, and is essentially responsible for the influx of glutamine inside the cells, inducing asparagine, serine and threonine efflux." (PMID 33669301, 2021). "One of the most prominent is the increase in glutamine consumption, which is reflected by the upregulation of the key glutamine transporters (SLC1A5 and the SLC7A5–SLC3A2 dimeric complex) at the surface of the tumour cells." (PMID 31819174, 2020).
tumor (continued). "While PDL1 was highly expressed in tumours with high SLCs and high SLC1A5 expression, PD1 + cells were mainly expressed with tumours with high SLC expression (p < 0.0001)." (PMID 31819174, 2020). "The glutaminolytic pathway provides both energy and building blocks for tumor growth and can be investigated by PET probes targeting the alanine serine cysteine-preferring transporter 2 (ASCT2 or SLC1A5)." (PMID 32857284, 2020). "We further performed quantitative RT-PCR to assay for mRNA levels of SLC1A5 (or ASCT2) and SLC7A5 (part of LAT1) and confirmed reduced ASCT2 and increased LAT1 expression in 22Rv CRPC compared to CWR22Res androgen-dependent tumours." (PMID 33237350, 2020). "Pharmacological blockade of SLC1A5 and SLC7A5 using a newly designed small molecule antagonist, V-9302, elicited a marked anti-tumor response in pre-clinical tumor models." (PMID 31652923, 2019). "Known inhibitors of SLC1A5 such as 6-diazo-5-oxo-l-norleucine (DON), Benzylserine, and L-γ-glutamyl-p-nitroanilide (GPNA) have been shown to effectively suppress tumor growth in vitro and in vivo." (PMID 31652923, 2019). "It was noted that SLC1A5 expression was higher in peripheral than intratumoral areas in MAS98.06 tumors, whereas MAS98.12 tumors were strongly stained throughout the tumor." (PMID 31088535, 2019). "The coexpression of SLC1A5, SLC7A11 and SLC7A5 proteins has yet to be determined in BC and is therefore important for understanding the potential transport of Gln in and out of tumour cells." (PMID 39843491, 2025). "Moreover, remarkable upregulation of SLC1A5, SLC3A2, and SLC7A5 were revealed by Western blotting in paired ESCC tumor and normal tissues." (PMID 39757767, 2025). "The high expression of SLC1A5 in luminal B tumours is perhaps not surprising because these tumours have greater demands for nutrients and energy, which are essential for cell survival and proliferation." (PMID 39843491, 2025). "ASCT2 (SLC1A5) is a sodium-dependent neutral amino acid transporter that facilitates glutamine uptake, fuelling the TCA cycle and mTORC1 activation, making it essential for glutamine-addicted tumours." (PMID 41154605, 2025). "ASCT2 (SLC1A5), as the major Gln transporter in tumor cells, exhibits high expression in tumor tissues, and its expression level is significantly negatively correlated with patient prognosis." (PMID 40137165, 2025). "Similarly, high expression of SLC1A5 and TALDO1 correlated with aggressive tumour features, including higher grade and increased proliferation." (PMID 41154605, 2025). "Using patient-derived tumor and adjacent non-cancerous tissues, we confirmed that expression of the SLC1A5, SLC7A5, and SLC38A1 is a rescue mechanism induced by GLS inhibition." (PMID 40707944, 2025). "Using patient-derived tumor and adjacent non-cancerous tissues, we found that expression of the SLC1A5, SLC7A5, and SLC38A1, and NUPR1 is a rescue mechanism induced by GLS inhibition." (PMID 40707944, 2025). "IHC analysis revealed that PHGDH, SLC1A5 and SLC38A2 are expressed in the GCs of TLSs in both normal and tumour colorectal tissues, suggesting that serine metabolism might play a critical role in GC formation." (PMID 40660426, 2025). "Furthermore, we evaluated the effect of the simultaneous knockdown of SLC1A5, SLC3A2, and SLC7A5 on tumor growth in a cell‐derived xenograft (CDX) mouse model." (PMID 39757767, 2025). "Furthermore, it has been confirmed that efficient uptake of glutamine and leucine through SLC1A5, SLC7A5, and SLC3A2 can enhance metabolic capacity and effector functions of NK and T cells targeting tumors for improved tumor recognition and infiltration." (PMID 39951434, 2025). "Notably, at the protein levels, SLC1A4 and SLC1A5 were highly expressed in most CRC tumors, and SLC7A11 was highly expressed in more than half of tumor samples." (PMID 39079386, 2024).
tumor (continued). "Consistent with our earlier observations about the NRF2/KLF5/SLC1A5 pathway in cultured cells, immunoblotting of the MT-101 tumor tissues showed that the accumulation of NRF2, KLF5, and SLC1A5 was obviously reduced upon CsA treatment and upon the CsA and CB-839 combination treatment." (PMID 38830868, 2024). "Inhibiting Gln flux by SLC1A5, SLC38A2, and SLC7A5 transporters with the V9302 small molecule antagonist boosts the tumor infiltration of CD8+ T cells in syngeneic breast cancer models and sensitizes experimental tumors to the programmed death-1 receptor 1 (PD-1) blockade." (PMID 39199642, 2024). "In addition to SLC1A5 and SLC7A5, there are other transport proteins that contribute to glutamine metabolism in tumor cells." (PMID 38459595, 2024). "Results show increased expression of SLC1A5 and FAP by flow cytometry and confocal imaging, and CD163 (confocal imaging) in HCC827 tumor slices incubated with REVs or when co-cultured with HCC827-GR tumor slices." (PMID 39431017, 2024). "Silibinin plays an anti-tumor role in GBM process, which may be achieved via inhibiting YY1/SLC1A5 pathway." (PMID 38410123, 2024). "SLC1A5 expression progressively increased during the pathogenesis of oral squamous cell carcinoma (OSCC), and it regulates glutamine metabolism or antioxidant function to mediate tumor progression." (PMID 39223142, 2024). "The RT‐PCR results demonstrated that mRNA expression levels of SLC7A11, SLC1A5, and GCLM were notably up‐regulated and SAT1 was down‐regulated in HCC patients' tumor tissues compared with their ANLTs, which were consistent with the results from TCGA database analysis." (PMID 35841206, 2023). "Concerning glutamine homeostasis, up-regulation of the specific transporter ASCT2 (SLC1A5) or the more generic L-type amino acid transporter 1 (LAT1, also known as SLC7A5), was observed in HCC tissue compared with adjacent non-tumor tissue, correlating with tumor size." (PMID 37108625, 2023). "Besides, when evaluating the impact of SLC1A5 and SLC38A1 on ferroptosis, different tumor types and heterogeneity should also be carefully considered." (PMID 36262284, 2022). "Expressions of four transcripts including L-type amino acid transporter 1 (SLC7A5), the high-affinity L-glutamine transporter (SLC1A5), glutaminase (GLS), and glutamate dehydrogenase 1 (GLUD1) were all significantly up regulated in T3 as compared with T1 and T2 tumours." (PMID 36615660, 2022). "As for protein expression, SLC1A5 was strong staining in tumor tissues but negative staining in normal tissues." (PMID 35419359, 2022). "Therefore, the potential target FRGs, SLC1A5, CD44 and NQO1, for tumor resistance treatment have important research value in the treatment of SCC drug resistance." (PMID 35501667, 2022). "Furthermore, the decrease of GLS1, SLC1A5, and c-Myc induced by QCSL was also found in tumor samples." (PMID 35058981, 2022). "In the present study, the ferroptosis-related gene SLC1A5 was identified as a potential prognostic biomarker for STAD, its upstream molecule miR-137 was explored, and the correlation between SLC1A5 and tumor-infiltrating immune cells and immune checkpoints in STAD was investigated." (PMID 35305616, 2022). "The tumor weight and volume in the sh-SLC1A5 group were significantly lower than those in the negative control group." (PMID 35419359, 2022). "Fourth, by which mechanisms glutamine transported by SLC1A5 prefers to meet the demand of tumor growth rather than promoting ferroptosis is not well defined." (PMID 35419359, 2022). "Multiple oncogenes are involved in reprogramming glutamine metabolism to drive fast proliferation in tumor cells, including MYC which is known to upregulate the glutamine transporter SLC1A5 to increase the glutamine uptake, and the enzymes GLS1 / 2 which convert glutamine to glutamate." (PMID 35148308, 2022).